TCAM1P (testicular cell adhesion molecule 1, pseudogene )
Synonyms: TCAM1
Gene: Long non-coding RNA gene on chromosome 17 (63,849,267 to 63,864,381, forward strand). Ensembl gene ENSG00000293480.
Diseases named in the same sentence as TCAM1P in open-access papers:
TCAM1P is named in the same sentence as 9 diseases in open-access papers, as found by Europe PMC text mining. Sharing a sentence is not in itself a finding about the gene and the disease. The quoted sentences say what the papers report.
cervical (1 paper, 2022). "In this study, we first proposed TCAM1P as a testis/cancer-specific pseudogene, and used a series of experimental data to verify its relationship with HPV, and analyzed its diagnosis value of high-grade cervical lesions and the mechanism of their high expression in cervical cancer." (PMID 35016697, 2022).
cervical cancer (1 paper, 2022). A primary or metastatic malignant neoplasm involving the cervix. "In our study, we found that EIF4A3 regulated the expression of TCAM1P, which means high expression of TCAM1P in cervical cancer is regulated by EIF4A3." (PMID 35016697, 2022). "To clarify the mechanism of high expression of TCAM1P in cervical cancer, we detected the expression of TCAM1P in the cytoplasm and nucleus." (PMID 35016697, 2022). "Results showed that only TCAM1P is the common DEPGs and the expression level of TCAM1P in cervical cancer is higher than normal cervix tissue in all datasets that detect TCAM1P." (PMID 35016697, 2022). "In our study, we also found that the expression of TCAM1P in HPV-positive cervical cancer is higher than HPV-negative cervical cancer at the tissue and cell levels." (PMID 35016697, 2022). "To further determine the role of TCAM1P in cervical cancer, we once again analyzed its expression level in cervical cancer based on multiple GEO data sets and found that its expression in cervical cancer was higher than that in normal cervical tissue." (PMID 35016697, 2022). "Results showed that the expression of TCAM1P in HPV16/18-positive cervical cancer is higher than in HPV-negative cervical cancer." (PMID 35016697, 2022). "This suggested the potential clinical value of TCAM1P in cervical cancer screening and targeted therapy, but more evidence is needed." (PMID 35016697, 2022). "Otherwise, TCAM1P promoted proliferation through regulating cell cycle and DNA replication, but more evidence needs to be provided to reveal the mechanism by which TCAM1P plays a role in cervical cancer." (PMID 35016697, 2022). "Otherwise, TCAM1P promote proliferation through regulating cell cycle and DNA replication, but more evidence needs to be provided to reveal the mechanism by which TCAM1P plays a role in cervical cancer." (PMID 35016697, 2022). "Cell function testing found that silenced the expression of TCAM1P in cervical cancer cell, the proliferation ability is significantly reduced." (PMID 35016697, 2022). "Survival analysis results showed that higher TCAM1P is a protective factor for patients with cervical cancer." (PMID 35016697, 2022). "However, when we analyzed the prognostic value of TCAM1P in cervical cancer, we found that high expression of TCAM1P is related to good prognosis." (PMID 35016697, 2022). "Moreover, we verified the relationship between TCAM1P and HPV and confirmed that HPV E6/E7 and EIF4A3 can regulate the expression of TCAM1P, which promoted the proliferation of cervical cancer cells." (PMID 35016697, 2022). "TCAM1P was specifically high-expressed in normal testicular tissue and cervical cancer." (PMID 35016697, 2022). "TCAM1P promotes the proliferation of cervical cancer cells and acts as promoter in cervical cancer." (PMID 35016697, 2022). "First, we compare the expression level of TCAM1P between HPV-positive cervical cancer and HPV-negative cervical cancer based on GEO datasets." (PMID 35016697, 2022). "In order to further verify that the expression of TCAM1P is related to HPV infection, we used RT-PCR to detect the expression of TCAM1P in different cervical cancer cells." (PMID 35016697, 2022). "Considering that HPV 16 and HPV 18 were the most common and most carcinogenic infection type, we further analyzed whether there is a differential expression of TCAM1P in HPV16/18-positive cervical cancer and HPV-negative cervical cancer." (PMID 35016697, 2022). "In this study, we found that the AUC of TCAM1P for CIN 2 or CIN3 are as high as 0.901 or 0.840, which means that TCAM1P can effectively diagnose high-grade cervical lesions and can be an effective method for cervical cancer screening." (PMID 35016697, 2022).
cervical cancer (continued). "Besides, the expression of TCAM1P was HPV dependent, with highest expression in HPV-positive cervical cancer tissues." (PMID 35016697, 2022).
liver fibrosis (1 paper, 2022). "Interestingly, the CC genotype of rs2727324 (SMARCD2, TCAM1P) was associated with depletion of Bacteroides dorei and Marinifilaceae, which we previously reported as depleted in subjects with liver fibrosis in the CCHC." (PMID 36386790, 2022).
lymph node metastasis (1 paper, 2022). "Result showed that TCAM1P expression is higher in patients with Lymph node metastasis than in non-metastasis while the difference was not statistically significant in the remaining groups." (PMID 35016697, 2022).
cancer (1 paper, 2022). A tumor composed of atypical neoplastic, often pleomorphic cells that invade other tissues. "In this study, we firstly proposed that TCAM1P is cancer/testis pseudogene and is regulated by HPV E6/E7 and EIF4A3." (PMID 35016697, 2022). "TCAM1P acted as cancer/testis specific pseudogene need more data to explore its value." (PMID 35016697, 2022). "Thus, in this study, we firstly proposed that TCAM1P is cancer/testis (CT) pseudogenes and is regulated by HPV E6/E7 and EIF4A3." (PMID 35016697, 2022).
TCAM1P also shares sentences with these, for which no sentence is quoted: infection (2 papers); acute myeloid leukemia (1); hepatocellular carcinoma (1); testicular germ cell tumor (1).